PSMD7 (proteasome 26S subunit, non-ATPase 7)
Diseases named in the same sentence as PSMD7 in open-access papers (continued):
Sharing a sentence is not in itself a finding about the gene and the disease.
tumor (11 papers, 2018 to 2025). "In this study, we assessed PSMD7 expression and investigated the underlying molecular events by which PSMD7 regulates tumor progression in non-small cell lung cancer (NSCLC)." (PMID 34234864, 2021). "The positive expression of PSMD7 was associated with poor differentiation (P = 0.019), tumor size ≥ 5 cm (P = 0.011), and the advanced tumor-node-metastasis (TNM) stage (P = 0.043)." (PMID 34512150, 2021). "Our results shed light on the important role of PSMD7 on HNSCC and suggest a potential association between PSMD7 and tumor immune infiltration as well as an underlying mechanism." (PMID 33687056, 2021). "IHC analysis demonstrated that the knockdown of PSMD7 resulted in a reduction in the number of Ki-67-positive cells within the tumor." (PMID 38494478, 2024). "The results of in vivo experiments demonstrated that the suppression of PSMD7 led to a significant inhibition of tumour growth." (PMID 38494478, 2024). "The tumor volume and weight of mice harboring PSMD7-silenced cells exhibited a remarkable reduction, whereas simultaneous SOX2 overexpression completely abrogated the antitumour effects of PSMD7 knockdown." (PMID 38494478, 2024). "Fourthly, as far we as we know, PSMD7 is overexpressed in many cancer cells, indicating the tumor-promoting role of PSMD7." (PMID 35037550, 2022). "We further confirmed that PSMD7 protein levels were higher in GC tissues than in tumor-adjacent tissues." (PMID 34512150, 2021). "PSMD7 is reported to be overexpressed in most carcinoma cells and its down-regulation contributed to decelerated tumor growth, inhibition of proteasomal function, induced cell apoptosis and attenuated activity of the mTOR/p70S6K pathway." (PMID 33391408, 2021). "We found that 47 of 80 (58.75%) GC tissues showed positive PSMD7 expression, whereas only 40.00% of adjacent non-tumor tissues positively expressed PSMD7 (P = 0.018)." (PMID 34512150, 2021). "Regarding the tumor grade, the expression of PSMD7 was significantly increased in grade 2 than in grade 1." (PMID 33687056, 2021). "In this study, we determined the difference in PSMD7 expression in GC and adjacent non-tumor tissues." (PMID 34512150, 2021). "In ESCC xenografts bearing mice with repression of PSMD7, we also proved that in vivo ability of PSMD7 inhibition suppresses tumor growth and induces apoptosis." (PMID 29632807, 2018). "Moreover, the PSMD7-knockout group exhibited significantly reduced tumour weight and volume compared to the control group." (PMID 38494478, 2024). "As a member of the DUBs family, proteasome 26 S subunit non-ATPase 7 (PSMD7) serves as an underlying tumour-promoting factor in multiple cancers." (PMID 38494478, 2024). "Knockdown of PSMD7 inhibited tumor growth in a xenograft mouse model." (PMID 34234864, 2021). "Moreover, PSMD7 silencing inhibited tumor growth and enhanced the sensitivity of GC cells to DDP treatment in mice." (PMID 34512150, 2021). "PSMD7 knockdown significantly repressed GC tumor growth in nude mice (P < 0.05)." (PMID 34512150, 2021). "PSMD7 protein levels were detected in 80 pairs of GC and tumor-adjacent tissues using IHC staining." (PMID 34512150, 2021). "Finally, we performed IHC staining and found PSMD7 mainly in the cytoplasm in normal tissues, whereas PSMD7 staining was detected in both the cytoplasm and nuclei in tumor tissues." (PMID 34234864, 2021). "Knockdown of PSMD7 deferred tumor growth in comparison with controls." (PMID 29632807, 2018). "Summary, PSMD7 knockdown induces impaired tumor growth in vivo." (PMID 29632807, 2018).
tumor (continued). "Furthermore, PSMD7 downregulation contributed to decelerated tumor growth, inhibition of proteasomal function, induced cell apoptosis and attenuated activity of mTOR/p70S6K pathway in vivo." (PMID 29632807, 2018). "Furthermore, we also found that PSMD7 knockdown in vivo suppressed the tumor growth using ESCC tumor models." (PMID 29632807, 2018). "Importantly, knockdown of PSMD7 markedly inhibited LUAD tumor growth in a xenograft mouse model." (PMID 34234864, 2021). "Therefore, PSMD7 functions in a variety of tumor types, and blocking it may be a promising strategy to inhibit tumor growth." (PMID 34234864, 2021). "Furthermore, PSMD7 silencing inhibited GC tumor growth in vivo." (PMID 34512150, 2021). "In summary, PSMD7 was highly expressed in GC and contributed to the malignant behavior and DDP resistance of tumor cells by stabilizing RAD23B." (PMID 34512150, 2021). "PSMD7 knockdown induced cell cycle arrest, senescence, and apoptosis and suppressed LUAD tumor growth in a xenograft mouse model." (PMID 34234864, 2021). "Although the latent mechanisms of action of PSMD7 in patients with PC may be diverse and complex, PMSD7 remains an essential gene involved in oncogenesis and tumour progression." (PMID 38494478, 2024). "Moreover, PSMD7 knockdown suppressed the in vivo growth of GC cells and enhanced the efficiency of DDP treatment for tumor-bearing mice." (PMID 34512150, 2021). "PSMD7 knockdown markedly reduced the percentage of Ki-67 positive cells but increased the number of TUNEL-stained cells in xenograft tumor tissues with or without DDP treatment (P < 0.05)." (PMID 34512150, 2021). "A prominent cleaved PARP band was detected in PSMD7 knockdown tumor cells, whereas no PARP cleavage band was observed in control groups." (PMID 29632807, 2018). "Also, the cleavage of PARP band was detected in PSMD7 knockdown tumor cells, but not in control groups." (PMID 29632807, 2018). "The 26S proteasome non-ATPase regulatory subunit (PSMD) 2 (PSMD2), PSMD7, and PSMD14 proteins participate in the ubiquitin-proteasome system, which plays a potential role in the proliferation and progression of tumor cells." (PMID 37350936, 2023).
cancer (9 papers, 2011 to 2024). A tumor composed of atypical neoplastic, often pleomorphic cells that invade other tissues. "Increased PSMD7 influenced several key pathway associated with carcinogenesis and cancer process via GSEA." (PMID 33687056, 2021). "PSMD7 has been reported as a cancer‐associated signature in a variety of tumors, such as breast 17, 18, prostate 19, and bladder cancers." (PMID 29632807, 2018). "In addition, mounting evidence suggests a robust association between elevated PSMD7 expression and enhanced cancer cell proliferation across various malignancies and can result in poor prognosis." (PMID 38494478, 2024). "There is growing evidence that dysregulation of PSMD7 not only inactivates tumour suppressors, but also upregulates oncogene function in various cancers, leading to carcinogenesis." (PMID 38494478, 2024). "When we silenced PSMD7, the viability of cancer cells was inhibited." (PMID 35037550, 2022). "PSMD7 was examined in various cancers with the Sangerbox database." (PMID 33687056, 2021). "However, little knowledge about the cellular biological role of PSMD7 is known, and further research is needed to clarify its exact function in normal cells, particularly in cancer cells." (PMID 29632807, 2018). "However, there is little knowledge about the cellular mechanism of PSMD7 and its exact biological function, especially in cancer cells." (PMID 29632807, 2018). "Taken together, PSMD7 exhibits pro‐cancer characteristics, which suggests PSMD7 could be a potential molecular target for ESCC therapy." (PMID 29632807, 2018). "PSMD7, a 19S proteasome subunit, is overexpressed in most carcinoma cells." (PMID 29632807, 2018). "PSMD7 (26S proteasome non-ATPase regulatory subunit 7) has been reported as overexpressed in a variety of tumors and is hypothesized to be involved in maintenance of proteasome function in cancer cells through its roles in mediating endosomal trafficking and protein recycling." (PMID 32370304, 2020). "Therefore, we found PSMD7 is differently expressed in cancer cell lines." (PMID 29632807, 2018). "Therefore, we hypothesized that PSMD7 maybe probably involved in the maintenance of proteasomal function in cancer cells." (PMID 29632807, 2018). "Proteasome 26S non-ATPase subunit 7 (PSMD7) is a 19S regulator subunit independent of ATP that, in recent years, has been found to be overexpressed in many types of cancer cells." (PMID 35037550, 2022). "Based on the inhibited activity of the mTOR pathway in PSMD7 knockdown ESCC cell line, whether the anti‐cancer effect of PSMD7 knockdown in vivo through mTOR/p70S6K inhibition was evaluated." (PMID 29632807, 2018).
PSMD7 also shares sentences with these, for which no sentence is quoted: Parkinson disease (2 papers); prostate carcinoma (2); acute myeloid leukemia (1); amyotrophic lateral sclerosis (1); cervical cancer (1); Epstein-Barr virus infection (1); familial melanoma (1); Follicular Cyst (1); head and neck cancer (1); head and neck squamous cell carcinoma (1); hematological malignancies (1); Hypertension (1); kidney renal cancer (1); liver cancer (1); lymph node metastases (1); mantle cell lymphoma (1); mastitis (1); melanoma (1); multiple myeloma (1); oral squamous cell carcinoma (1); oropharyngeal carcinoma (1); ovarian carcinoma (1); prion disease (1); rheumatoid arthritis (1); tongue squamous cell carcinoma (1).